IFITM2 (interferon induced transmembrane protein 2)
Description:
IFN-induced antiviral protein which inhibits the entry of viruses to the host cell cytoplasm, permitting endocytosis, but preventing subsequent viral fusion and release of viral contents into the cytosol. Active against multiple viruses, including influenza A virus, SARS coronaviruses (SARS-CoV and SARS-CoV-2), Marburg virus (MARV), Ebola virus (EBOV), Dengue virus (DNV), West Nile virus (WNV), human immunodeficiency virus type 1 (HIV-1), hepatitis C virus (HCV) and vesicular stomatitis virus (VSV). Can inhibit: influenza virus hemagglutinin protein-mediated viral entry, MARV and EBOV GP1,2-mediated viral entry, SARS-CoV and SARS-CoV-2 S protein-mediated viral entry and VSV G protein-mediated viral entry. In hepatocytes, IFITM proteins act in a coordinated manner to restrict HCV infection by targeting the endocytosed HCV virion for lysosomal degradation. IFITM2 and IFITM3 display anti-HCV activity that may complement the anti-HCV activity of IFITM1 by inhibiting the late stages of HCV entry, possibly in a coordinated manner by trapping the virion in the endosomal pathway and targeting it for degradation at the lysosome.
Synonyms: DSPA2c; 1-8D
Tractability: Antibody: UniProt places it where antibodies can reach, with high confidence; its Gene Ontology location is reachable by antibodies, with high confidence; UniProt predicts a signal peptide or a membrane-spanning region. PROTAC: ubiquitination databases record sites on it.
Gene: Protein-coding gene on chromosome 11 (303,655 to 309,397, forward strand). Ensembl gene ENSG00000185201.
Subcellular location: Cell membrane; Lysosome membrane; Late endosome membrane
Subcellular location (Human Protein Atlas): Cell Junctions; Nucleoplasm
Pathways (Reactome):
Immune System: Interferon alpha/beta signaling
Gene Ontology:
Biological process: cellular response to interferon-beta; host-mediated suppression of symbiont invasion; negative regulation of viral genome replication; response to interferon-alpha; response to interferon-beta; response to type II interferon; response to virus; defense response to virus; immune response; type I interferon-mediated signaling pathway
Cellular component: late endosome membrane; lysosomal membrane; protein-containing complex; plasma membrane; membrane
Genetic constraint (gnomAD): Loss-of-function variants: 5 observed, 6.62 expected, observed/expected ratio (o/e) 0.76, 90% interval 0.39 to 1.55. That is too few expected variants to judge how well the gene tolerates losing a copy. Missense variants: 159 observed, 180.07 expected, observed/expected ratio (o/e) 0.88, 90% interval 0.77 to 1.01. Synonymous variants: 76 observed, 69.33 expected, observed/expected ratio (o/e) 1.1, 90% interval 0.91 to 1.33.
Homologues: Orthologues: chimpanzee IFITM2 (98% identical), mouse Ifitm2 (64% identical), mouse Ifitm3 (64% identical), rat Ifitm3-ps2 (58% identical), rat Ifitm1 (53% identical), mouse Ifitm7 (52% identical), mouse Ifitm1 (51% identical). Paralogues in human: IFITM3 (91% identical), IFITM1 (65% identical), IFITM10 (34% identical), IFITM5 (29% identical).
Diseases named in the same sentence as IFITM2 in open-access papers:
IFITM2 is named in the same sentence as 68 diseases in open-access papers, as found by Europe PMC text mining. Sharing a sentence is not in itself a finding about the gene and the disease. The quoted sentences say what the papers report.
viral infection (23 papers, 2012 to 2025). "Both IFITM2 and 3 are generally thought to broadly inhibit viral infection; however, their relationship with CVB is poorly understood." (PMID 39772131, 2024). "SARS-CoV-2 Spike protein was shown to interact with IFITM proteins and utilize IFITM2 for efficient viral infection, while depletion of IFITM2 substantially reduced infectious virus production in vitro." (PMID 39026668, 2024). "The stark response to viral infection shown in the transcriptional increase of factors such as Ifitm2, Irf7, Stat1, and Eif2a, among others, indicates a heart actively mounting a host response to the invading SARS-CoV-2." (PMID 37081485, 2023). "Meanwhile, the activation of IFITM2 and IL-6 forms a reciprocally positive feedback loop to make MM malignant progenitor cells act out the expression pattern with virus infection." (PMID 36131282, 2022). "In accordance with hijacking of IFITMs for efficient SARS-CoV-2 infection, knockdown (KD) of endogenous IFITM2 expression in human lung cells strongly reduced viral infection and infectious virus production." (PMID 35543509, 2022). "A greater number of genes are upregulated in DCs after MRV infection, many of which are involved in the innate immune response (i.e. Ifit1, Ifit3, Mx1, Gbp2, Oasl1, Isg15, Ccr1, Ifitm2, Oaxl2, Casp1, Casp4) that would be predicted in response to a viral infection." (PMID 38895117, 2024). "Interferon-induced transmembrane protein 2 (IFITM2) is involved in repressing viral infection." (PMID 38802621, 2024). "Additionally, the immunomodulatory genes transmembrane protein 2 (IFITM2) and alpha-2 macroglobulin (A2M) were both upregulated in regions of viral infection." (PMID 36968839, 2023). "Given that the endocytic pathway could mediate IFITM restriction of viral infection, we hypothesized that overexpressed IFITM2 might affect endosomal compartments to interfere with EMCV infection in HEK293 cells." (PMID 37112847, 2023). "One family of ISGs is the IFN-induced transmembrane proteins (IFITMs), including IFITM1, IFITM2, and IFITM3, which limits the viral infection by various viruses." (PMID 41465488, 2025). "These included IFITM2 and IFITM3, IFIT family members which play a role in viral infection and SPOCK2, upregulated upon virus infection and recognized as protective against influenza infection." (PMID 39026668, 2024). "IFN-induced transmembrane proteins 2 and 3 (Ifitm2, 3) belong to IFITM proteins that are the cofactors for efficient virus infection in human cell types, including SARS-CoV-2 infection and acute/chronic hepatitis C virus infection." (PMID 37719192, 2023). "Our further analysis demonstrated that IFITM2, KMO, LIPG genes exerted the most obvious inhibition against viral infections in this study." (PMID 35235615, 2022). "Meanwhile, IFI6, IFITM2, ISG15, and LDHB were highly expressed in memory CD4+T cells, which were crucial for cell hypermetabolism and defense against virus infection." (PMID 35095832, 2021). "Previous studies revealed that IFITM2 and IFITM3 (two structurally related cell plasma membrane proteins) interrupt early steps entry and/or uncoating of the viral infection." (PMID 22397681, 2012). "It has been previously shown that innate immune activation and virus infection may induce ACE2 and IFITM2 expression." (PMID 35543509, 2022). "Indeed, module 3 included three IFN-induced transmembrane (IFITM) genes (IFITM1, IFITM2, IFITM3), involved in the restriction of multiple viruses, that were overexpressed in patients with viral infection and positively correlated with severity." (PMID 33765435, 2021). "Over-expressing IFITM1 significantly enhanced KSHV infection of cells; IFITM3 moderately enhanced KSHV infection while IFITM2 did not alter the viral infection." (PMID 29269892, 2017).
viral infection (continued). "Convergently evolved amino acids between primates and rodents were found in the C-terminus of IFITM2 and IFITM3 (data not shown), a crucial region for antiviral activity, supporting the association between viral infections and the evolution of IR-IFITM genes." (PMID 23166625, 2012). "It is not only IRF7 that responds to viral infection, as this is also common to a group of interferon-stimulated genes (ISG), such as Orthomyxovirus resistance gene (Mx), oligoadenylate synthetase (OAS), ISG15, and Interferon-induced transmembrane protein 2 (IFITMs)." (PMID 36164603, 2022). "Overexpression of IFITM1, IFITM2, and IFITM3 proteins did not restrict the entry of pseudoparticles carrying arenavirus envelope glycoproteins and live virus infection." (PMID 35283811, 2022). "Finally, we found that genes closest to sites with significant negative coefficients for age included IFITM1, IFITM2, and IFITM3, which are interferon response genes that are activated following viral infections, such as the hepatitis C virus." (PMID 39637179, 2024).
COVID-19 (15 papers, 2020 to 2024). A disease caused by infection with severe acute respiratory syndrome coronavirus 2. "Our observation that IFITM2 dependency is maintained by VOCs also further underlines that, against the odds, this cellular “antiviral-turned-proviral” factor represents a potential target for therapeutic or preventive approaches in COVID-19." (PMID 35543509, 2022). "Based on the PBMC samples from the cellxgene dataset, the expression data of TNFSF10 and IFITM2 in COVID-19 patients were obtained by Single-cell RNA-seq analysis." (PMID 36555339, 2022). "This inability to activate IRF3 correlated with decreased expression of the interferon-stimulated gene IFITM2, examined in an expanded cohort of healthy, mild and moderate COVID-19 monocytes after stimulation with SARS-CoV-2." (PMID 36572683, 2022). "They identified neutrophils (IFITM2, IFITM1, H3-H3B, SAT1 and S100A8) and macrophage cluster-1 (CCL8, CCL3, CCL2, KLF6 and SPP1) as the main immune cell subsets associated with severe COVID-19 cases." (PMID 34109284, 2021). "Changes in the expression levels of TNFSF10 and IFITM2 in CD14+/CD16+ monocytes may affect the immune response of COVID-19 patients." (PMID 36555339, 2022). "Among the identified gene signatures, IFITM2, IFITM1, H3F3B, SAT1, and S100A8 gene signatures were highly associated with neutrophils, while CCL8, CCL3, CCL2, KLF6, and SPP1 were associated with macrophage cluster-1 in severe-COVID-19 patients." (PMID 33138195, 2020). "Next, we performed differential analysis of two networks and identified group of genes that changed their interactions with three DE genes- IFITM2, FAM65B and SELL, across COVID-19 vs healthy ILC networks." (PMID 39026668, 2024). "Most of DE genes predicted were conserved across the two different analyses, including the genes IFITM2, SELL, and FAM65B, which were also predicted to be significantly downregulated in LT COVID-19 patients compared with healthy participants." (PMID 39026668, 2024). "Within the list of significantly DE genes, interferon-induced transmembrane protein 2 (IFITM2), FAM65B and SELL were downregulated in all ILC subsets in COVID-19 patients compared with healthy controls." (PMID 39026668, 2024). "IFITM2 and TNFSF10 were the two DEGs that overlapped when comparing the gene expression levels from patients of COVID-19, cancer, ARDs and PF." (PMID 36555339, 2022). "High expression of IFITM2 and IFITM3 has been widely detected in individuals with COVID-19." (PMID 38077419, 2023). "IFITM2 was upregulated in COVID-19 patients without cancer, which can be supported by the conclusion from previous study that IFITM2 inhibited the entry of SARS-CoV-2 virus." (PMID 36555339, 2022). "Targeting TNFSF10 and IFITM2 in CD14+ and CD16+ monocytes may affect the immune response of COVID-19 patients with cancer." (PMID 36555339, 2022). "COVID-19 neutrophils preferentially transitioned from the apex of the trajectory, which was an immature state (TOP2A-expressing) to an IFNactive state characterized by IFITM1, IFITM2 and IFI6 expression (clusters 1–4 and 5; Online Atlas) and activation of type I IFN signaling pathways." (PMID 34782790, 2022). "However, compared with recovered COVID-19 patients without cancer, IFITM2 was downregulated in COVID-19 patients with hematologic cancer (exitus)." (PMID 36555339, 2022). "In module 2, enhanced expression of glycolysis (GAPDH and TPI1) and IFN response (IFITM2, IFITM1, IFITM3, IFNGR2, and ISG20) genes in human COVID-19 patients, particularly severely ill patients, may promote the differentiation of unswitched memory B cells into plasmablasts." (PMID 33936072, 2021). "Based on the GSE153610 dataset, compared with recovered COVID-19 patients without cancer, TNFSF10 were upregulated in monocytes of cancer patients infected with SARS-CoV-2, while IFITM2 were downregulated." (PMID 36555339, 2022). "In addition, the common DEGs among ARDS, PF and COVID-19 patients with and without cancer are TNFSF10 and IFITM2." (PMID 36555339, 2022).
gastric cancer (10 papers, 2011 to 2024). A primary or metastatic malignant neoplasm involving the stomach. "Evidence showed that IFITM2 was highly expressed in gastric cancer and renal clear cell carcinoma, which associates with poor survival." (PMID 36555339, 2022). "In gastric cancer cohorts, the upregulation of IFITM2 is associated with accelerated disease progression and shorter survival time." (PMID 29162141, 2017). "According to some studies, IFITM2 is abnormally expressed in esophageal cancer, lung cancer, gastric cancer, glioma, and affects biological functions." (PMID 38802621, 2024). "Our previous study showed that IFITM2 activates the TGF-β1 pathway in gastric cancer to promote epithelial-mesenchymal transition." (PMID 38802621, 2024). "Univariate regression analysis revealed that the factors affecting OS in patients with gastric cancer were age (p < 0.001), T stage (p = 0.004), N stage (p < 0.001), M stage (p < 0.001), histologic grade (p < 0.001) and IFITM2 expression level (p < 0.001)." (PMID 38802621, 2024). "IFITM2 promotes gastric cancer progression by promoting cell migration and invasion, and inducing EMT, and interacts with the SARS-CoV-2 S at the cell surface and virus-cell fusion in early endosomes." (PMID 39228892, 2024). "Silencing of IFITM2 in gastric cancer cells decreased cell proliferation, migration, and metastasis, while IFITM2 depletion in a mouse model resulted in dramatic decreases in tumor size." (PMID 29162141, 2017). "The effect of IFITM2 on the invasion and migration of gastric cancer was further investigated." (PMID 38802621, 2024). "Moreover, interferon-induced transmembrane protein 2 (IFITM2) promotes gastric cancer growth and metastasis, within which m6A was hypomethylated (bladder cancer tissues vs. normal adjacent tissues) and enriched in coding sequence (CDS)." (PMID 34868913, 2021). "IGF1/IGF1R/STAT3 signaling promoted IFITM2 expression and gastric cancer growth and metastasis." (PMID 32851683, 2020). "Further, IFITM2 was significantly up-regulated and induced after activation of beta-catenin signaling in colorectal cancers, and it was also reported to promote gastric cancer growth and metastasis through the insulin-like growth factor (IGF1)/IGF1 receptor (IGF1R)/STAT3 signaling pathway." (PMID 32765489, 2020). "In gastric cancer, IGF1/IGF1R/STAT3 signaling‐inducible IFITM2 promotes gastric cancer growth and metastasis." (PMID 32851683, 2020).
Sepsis (6 papers, 2022 to 2025). Sepsis is defined as life-threatening organ dysfunction caused by a dysregulated host response to infection. "Although this study provides preliminary evidence for S100A11, QPCT, and IFITM2 as potential biomarkers of sepsis, several limitations remain." (PMID 39854580, 2025). "The prognosis of sepsis patients was strongly linked to S100A11, QPCT, and IFITM2 based on meta-analysis and survival analysis(P < 0.05).GSEA analysis showed that S100A11, QPCT, and IFITM2 were significantly enriched in ribosome-related pathways." (PMID 39854580, 2025). "Here, we initially discovered that cell surface ENO1 on CD4+ T cells acted as a receptor anchored by NET-MPO, facilitating NET accumulation around CD4+ T cells and recruiting IFITM2 as a DNA sensor in sepsis-induced immunosuppression." (PMID 40892462, 2025). "NETs-MPO-anchored ENO1 mediates the role of NETs-DNA in promoting Treg differentiation and function in sepsis-induced immunosuppression via a newly identified DNA sensor IFITM2." (PMID 40892462, 2025). "In the sepsis group, the qPCR results showed that S100A11, QPCT, and IFITM2 expression levels were significantly higher in the sepsis group(P < 0.05)." (PMID 39854580, 2025). "Our platelet transcriptomic and proteomic data indicate other IFITMs, including IFITM1 and IFITM2, are also increased in sepsis and IFN-induced inflammation." (PMID 36194487, 2022). "In this study, S100A11, QPCT, and IFITM2 were screened as new potential biomarkers for sepsis." (PMID 39854580, 2025). "The expression of IFITM2 in splenic Tregs was also reduced in Eno1fl/fl Cd4Cre mice during septic immunosuppression, suggesting that the upregulation of IFITM2 in sepsis is related to ENO1." (PMID 40892462, 2025). "This indicates that the control of S100A11, QPCT, and IFITM2 expression could be significant in the development of sepsis." (PMID 39854580, 2025). "In summary, this study provides preliminary evidence for S100A11, IFITM2, and QPCT as novel sepsis biomarkers." (PMID 39854580, 2025). "The findings indicated a positive correlation between the survival of sepsis patients and the levels of S100A11, QPCT, and IFITM2 expression." (PMID 39854580, 2025). "The meta-analysis findings indicated variations in the levels of S100A11, QPTC, and IFITM2 expression among sepsis patients who survived and those who did not." (PMID 39854580, 2025). "The present study revealed the expression pattern, cell line localization, and functional enrichment of S100A11, IFITM2, and QPCT in macrophages, aiming at an in-depth exploration of the roles of S100A11, IFITM2, and QPCT in sepsis to evaluate their potential as novel biomarkers." (PMID 39854580, 2025).
HIV-1 infection (5 papers, 2018 to 2024). The type species of lentivirus and the etiologic agent of acquired immunodeficiency syndrome (AIDS). "Moreover, Δ20-IFITM2, a N-terminal 20-aa truncated isoform of IFITM2, which is derived from an alternatively initiated RNA transcript, demonstrated a more potent suppression on HIV-1 infection than that by full-length wild-type IFITM2." (PMID 30687247, 2018). "On the other hand, HIV-1 infection triggers the over-expression of several RFs genes, including IFITM1, IFITM2, IFITM3, MX1, MX2, TETHERIN, IFN1a, and IFNR." (PMID 39476027, 2024). "Consistent with our entry results, we observed that IFITM2/3 knockout greatly enhanced infection by HIV-1∆env(VSV-G), but had a much less pronounced effect on wild-type HIV-1 infection." (PMID 29554922, 2018). "Indeed, we have observed that FLAG-tagged IFITMs are approximately 25–30% more potent than their WTs to inhibit HIV-1 infection; however, the order of potency in inhibition for the untagged WT IFITMs and FLAG-IFITMs remains the same, that is, IFITM3 > IFITM2 > IFITM1." (PMID 30087232, 2018). "The results showed that mRNA levels of already known host restriction factors which inhibit HIV-1 infection, TRIM5α, MX2, SAMHD1, SERINC3, SERINC5, IFITM2, IFITM3, ApoE, and PSGL-1 were not significantly elevated by γ-IFN." (PMID 35883685, 2022).